ALDOA (aldolase, fructose-bisphosphate A)
Description:
Catalyzes the reversible conversion of beta-D-fructose 1,6-bisphosphate (FBP) into two triose phosphate and plays a key role in glycolysis and gluconeogenesis. In addition, also functions as a scaffolding protein (By similarity). In response to glucose deprivation, FBP dissociates from aldolase and acts as an adapter that promotes AMP-activated protein kinase (AMPK) activity: mechanistically, associates with transient receptor potential channels TrpV (TRPV1-TRPV4), promoting inhibition of the V-ATPase complex on lysosomes and AMPK activation via the AXIN1-STK11/LKB1 axis (By similarity).
Synonyms: ALDA; GSD12; HEL-S-87p
Tractability: Small molecule: a structure with a bound ligand is known; it has a high-quality binding pocket. Antibody: its Gene Ontology location is reachable by antibodies, with high confidence. PROTAC: UniProt records ubiquitination sites on it; ubiquitination databases record sites on it; its protein half-life has been measured.
Target class: Enzyme; Lyase
Gene: Protein-coding gene on chromosome 16 (30,064,164 to 30,070,457, forward strand). Ensembl gene ENSG00000149925.
Subcellular location: Cytoplasm, myofibril, sarcomere, I band; Cytoplasm, myofibril, sarcomere, M line
Subcellular location (Human Protein Atlas): Cytosol
Pathways (Reactome):
Metabolism: Gluconeogenesis; Glycolysis
Hemostasis: Platelet degranulation
Immune System: Neutrophil degranulation
Gene Ontology:
Molecular function: cadherin binding; cytoskeletal protein binding; fructose binding; fructose-bisphosphate aldolase activity; identical protein binding; protein binding; RNA binding; actin binding; tubulin binding
Biological process: ATP biosynthetic process; binding of sperm to zona pellucida; canonical glycolysis; fructose 1,6-bisphosphate metabolic process; fructose metabolic process; glycolytic process; muscle cell cellular homeostasis; positive regulation of insulin secretion involved in cellular response to glucose stimulus; regulation of cell shape; striated muscle contraction; actin filament organization; gluconeogenesis; protein homotetramerization
Cellular component: actin cytoskeleton; extracellular exosome; extracellular region; membrane; nucleus; sperm head; cytosol; ficolin-1-rich granule lumen; I band; platelet alpha granule lumen; secretory granule lumen; tertiary granule lumen; M band
Genetic constraint (gnomAD): Loss-of-function variants: 26 observed, 43.97 expected, observed/expected ratio (o/e) 0.59, 90% interval 0.43 to 0.82. The upper end of that interval is the gene's LOEUF score, 0.82, which puts it in group 3 of 6, group 1 being the genes least tolerant of losing a copy. Missense variants: 498 observed, 566.46 expected, observed/expected ratio (o/e) 0.88, 90% interval 0.82 to 0.95. Synonymous variants: 258 observed, 229.45 expected, observed/expected ratio (o/e) 1.12, 90% interval 1.01 to 1.25.
Homologues: Orthologues: macaque ALDOA (99% identical), chimpanzee ALDOA (97% identical), rabbit ALDOA (96% identical), guinea pig ALDOA (95% identical), dog ALDOA (94% identical), rat Aldoa (88% identical), mouse Aldoa (85% identical), pig ALDOA (82% identical), mouse Aldoart1 (82% identical), mouse Aldoart2 (81% identical), rat Aldoart2 (81% identical), tropical clawed frog aldoa (78% identical), and 6 more. Paralogues in human: ALDOC (71% identical), ALDOB (61% identical).
Diseases named in the same sentence as ALDOA in open-access papers:
ALDOA is named in the same sentence as 146 diseases in open-access papers, as found by Europe PMC text mining. Sharing a sentence is not in itself a finding about the gene and the disease. The quoted sentences say what the papers report.
lung carcinoma (37 papers, 2007 to 2025). "ALDOA, when overexpressed, has been associated with increased proliferation and metastasis in lung cancer cells." (PMID 38256214, 2024). "ALDOA not only responds to cisplatin in lung cancer cell lines but our observations also identified several standard chemotherapeutic drugs associated with ALDOA expression in lung cancer, including paclitaxel and vinorelbine." (PMID 32188842, 2020). "In this study, we showed that the level of Aldolase A (ALDOA) expression is significantly associated with the IC50 value of chemotherapy drugs in lung cancer." (PMID 32188842, 2020). "Aldolase A (ALDOA) is a key enzyme of glycolysis, which can regulate metabolism and proliferation and is associated with the progression, immune infiltration, and prognosis of a variety of cancers, including lung cancer." (PMID 36714109, 2022). "This lactate-mediated signaling represents a critical mechanism by which ALDOA influences the tumor microenvironment, underscoring the significance of ALDOA in influencing lung cancer progression via metabolic pathways." (PMID 40520908, 2025). "Elevated expression of ALDOA has been observed in lung cancer patient samples of different subtypes, with studies indicating its association with tumour progression and poor prognosis." (PMID 41154605, 2025). "Mechanistically, ALDOA promotes lung cancer metastasis by activating the HIF-1α/MMP9 axis, enhancing cell invasion and migration." (PMID 41154605, 2025). "In lung cancer, ALDOA exhibits a tumor-promoting effect through the EGFR/MAPK signaling cascade and modulation of HIF-1α signaling." (PMID 39755705, 2025). "In fact, the glycolytic enzyme ALDOA has been shown to foster the growth and metastasis of tumors such as liver or lung carcinomas, osteosarcoma, and others." (PMID 39201614, 2024). "At the same time, ALDOA has been proven to regulate the progression and metastasis of lung cancer through a variety of ways." (PMID 35804089, 2022). "The study has shown that the overexpression of ALDOA increases the migration and invasion of lung cancer cell lines in vitro and the formation of metastatic lung cancer in vivo." (PMID 36506331, 2022). "The results suggest the benefits of compounds that block ALDOA/γ-actin interaction for patients with lung cancer and other metastatic cancers with minimal toxicity." (PMID 35721191, 2022). "An interaction of γ-actin and glycolytic enzyme aldolase A (ALDOA) was found in metastatic lung cancer cells." (PMID 35721191, 2022). "High expression of ALDOA is also related to galactose metabolism and colorectal cancer, lung cancer, and gastric cancer." (PMID 35869254, 2022). "ALDOA is involved in lung cancer metabolic reprogramming and metastasis, and a block of the γ-actin/ALDOA interaction by raltegravir decreased metastasis both in vitro and in vivo, and prolonged survival rate in vivo." (PMID 35721191, 2022). "We previously observed that ALDOA expression correlated more strongly with poor prognosis in lung cancer." (PMID 35404841, 2022). "Our research not only proves that the regulation of phospholipase D depends on PLD1 in lung cancer, but it also shows that ALDOA is required as a gatekeeper for glycolytic conversion and intermediate production." (PMID 35127525, 2021). "In lung cancer, overexpression of ALDOA is reported to promote lung cancer cell proliferation and metastasis." (PMID 34925439, 2021). "We further established an overexpression model in CL1-0 and confirmed that the expression level of ALDOA indeed conferred lung cancer cell viability and radiation response." (PMID 35127525, 2021). "Our data confirm that ALDOA can coordinate with PLD1 by regulating the RNA levels of lung cancer patients." (PMID 35127525, 2021). "Samples of lung cancer have been noted to possess an overexpression of ALDOA, which enhances epithelial-mesenchymal transition." (PMID 34277450, 2021).
lung carcinoma (continued). "In lung cancer, activated HIF1α is a transcription factor that transactivates ALDOA and promotes the Warburg effect, increasing lactate production under hypoxia." (PMID 35008539, 2021). "An increase in the expression of ALDOA in CD133-positive lung cancer cells or a side population of cells compared with that of the control groups was observed." (PMID 32188842, 2020). "Our data also revealed that ALDOA triggered stemness in lung cancer cells, with the spheroids exhibiting initiation and growth abilities in vivo." (PMID 32188842, 2020). "We analyzed the expression of glycolysis-associated genes from several in silico studies, with our results demonstrating that ALDOA plays a unique role and correlates with lung cancer stemness." (PMID 32188842, 2020). "At the RNA level, we observed that ALDOA coordinates with TRAF4 or DUSP4 in a TCGA lung cancer patient cohort." (PMID 32188842, 2020). "We validated that ALDOA indeed promotes lung cancer cell spheroid formation in an enzyme activity-independent manner." (PMID 32188842, 2020). "Taken together, these results demonstrate that ALDOA plays a key role in lung cancer stemness and tumor initiation." (PMID 32188842, 2020). "In this study, we showed that the glycolysis enzyme aldolase A (ALDOA) is correlated with the IC50 values of chemotherapy drugs in lung cancer cell lines." (PMID 32188842, 2020). "Via data searches and manipulation, we observed that the ALDOA RNA levels were positively correlated with the IC50 values of chemotherapy drugs such as cisplatin in a lung cancer cell panel according to two independent analyses." (PMID 32188842, 2020). "ALDOA stabilizes the HIF1α protein and forms a positive feedback pathway to promote lung cancer metastasis." (PMID 31601833, 2019). "Since the effect of ALDOA on lung cancer was reported in the previous studies, microarray datasets focused on lung cancer was used to detect AA genes, which were verified in other tumors." (PMID 28191039, 2017). "Recently, a new role of ALDOA has been proposed, given that ALDOA is highly expressed in a variety of malignant cancers, including human lung cancer, osteosarcoma, colorectal cancer, oral squamous cell carcinomas and hepatocellular carcinomas." (PMID 28191039, 2017). "To examine if ALDOA is required for lung cancer cell migration, we depleted ALDOA in NCI-H520 cells by stably expressing two independent shRNAs specific to ALDOA." (PMID 24465716, 2014). "ALDOA has been expressed in a variety of cancers, such as lung cancer, renal cell and hepatocellular carcinoma." (PMID 25379943, 2014). "Further, we demonstrated that depletion of ALDOA in lung cancer cells reduces its tumorigenicity and capability of migration." (PMID 24465716, 2014). "In cluster 6, the upregulated FTL (65 fold in our study) and ALDOA (7 fold in our study) were regulated by hypoxia inducible factor (HIF) during lung cancer." (PMID 23122428, 2012). "ALDOA enzyme (up), originally found to be up-regulated in lung cancer, was determined to be an indicator of poor prognosis in RCC patients in combination with gamma-enolase." (PMID 19455236, 2007). "ALDOA has been revealed to be highly expressed in numerous malignancies, including human pancreatic, prostate, hepatocellular, cervical, bladder, gastric, and lung cancer." (PMID 39755705, 2025). "ALDOA interacts with γ-actin to promote lung cancer metastasis, which could be targeted by an antiretroviral agent that targets HIV integrase (raltegravir)." (PMID 36030248, 2022). "Similarly, low FBP1 expression was also related to improved prognosis of lung cancer first progression and post-progression survival, and vice versa, and ALDOA was correlated with poor prognosis." (PMID 35404841, 2022). "We found that ALDOA overexpression brought a high level of LC3B-II ratio in lung cancer cells." (PMID 35127525, 2021). "Lung cancer metastasis and metabolic reprogramming appears to be strongly dependent on ALDOA." (PMID 34277450, 2021).
lung carcinoma (continued). "Thus, ALDOA-PLD1 should be monitored in the future, and targeting the ALDOA/PLD1 axis should be developed as a therapy for lung cancer patients." (PMID 35127525, 2021). "To investigate the characteristics of ALDOA in lung cancer stem cells, we established two-way models, several of which indicated that ALDOA indeed promotes the sphere-forming ability of lung cancer cells in vitro and in vivo in the absence of aldolase enzyme activity." (PMID 32188842, 2020). "Considering these results, we hypothesized that ALDOA combats the effects of chemotherapy drugs in lung cancer." (PMID 32188842, 2020). "Therefore, we assessed the cell viability of several lung cancer cell lines and ALDOA overexpression models via an MTT assay." (PMID 32188842, 2020). "Clinical data from several available cohorts, including TCGA and meta-base 1000 patients with lung cancer, indicated that the ALDOA-Oct4-TRAF4/DUSP4 axis is a potential prognostic indicator and may be a therapeutic target." (PMID 32188842, 2020). "ALDOA is one of the key enzymes in glycolysis pathway; and, recently, ALDOA was discovered to be highly expressed in a variety of malignant cancers, including human lung cancer, osteosarcoma, colorectal cancer, oral squamous cell carcinomas, and hepatocellular carcinomas." (PMID 31240215, 2019). "Also the up-regulation of ALDOA has been reported in many cancer types, such as oral squamous cell carcinoma, hepatocellular carcinoma, and in RCC and of ALDOA in ccRCC, osteosarcoma, and lung cancer." (PMID 31484429, 2019). "Notably, elevated levels of ALDOA have been reported in tumor cells and cancer patient samples, including those from oral squamous cell carcinoma, osteosarcoma, hepatocellular cell carcinoma, and lung cancer." (PMID 40305883, 2025). "Moreover, HIF‐1α‐modulated ALDOA upregulated expression in lung cancer cells." (PMID 35615976, 2022). "ALDOA may be a biomarker to distinguish between lung cancer and COPD." (PMID 36714109, 2022). "Therefore, the regulatory role of ALDOA in lung cancer and the prediction of prognosis are obvious." (PMID 35804089, 2022). "Therefore, we claim the ALDOA/PLD1 axis as an independent prognostic factor for lung cancer." (PMID 35127525, 2021). "Therefore, we hypothesized that the ALDOA/PLD2 protein–protein interaction may be through the degradation mechanism of lung cancer cells." (PMID 35127525, 2021). "Thus, ALDOA regulates the stemness properties of lung cancer cells via the Oct4-DUSP4/TRAF4 axis." (PMID 32188842, 2020). "Six genes (PGK1, ENO2, GPI, PEKP, ALDOA, and ANGPTL4) were reported as hypoxia-related genes in lung cancer." (PMID 38248716, 2023). "HIF‐1α was also found to both modulate ALDOA expression and increase lactate levels, leading to upregulation of MMP9, thereby promoting an invasion of lung cancer cells in vitro and in vivo." (PMID 35615976, 2022). "Most importantly, the combination of ALDOA and PLD1 can be used as an independent prognostic factor and is correlated with several clinical parameters in lung cancer." (PMID 35127525, 2021). "The data indicated that the ALDOA and PLD1 protein levels were positively correlated with the relatively poor overall and disease-free survival rates among lung cancer patients." (PMID 35127525, 2021). "At the same time, along with alkylating agents or radiation exposure, ALDOA and PLD1 jointly support various aggressive cancer phenotypes and the metabolic reprogramming of lung cancer cells." (PMID 35127525, 2021). "Merging this evidence, we demonstrated that ALDOA and PLD1 coordinately endow lung cancer cells with resistance to alkylating agents and radiation." (PMID 35127525, 2021). "The same with the results we have developed from bioinformatics, ALDOA, ENTPD2, LDHA, TYMS were significantly increased in 5 lung cancer cell line, comparing with in 16HBE." (PMID 33858449, 2021).
lung carcinoma (continued). "The protein expression levels of ALDOA, ENTPD2, LDHA, TYMS and CAT were investigated in 5 lung cancer cell lines (A549, H460, H1299, H1975, PC9), normal airway epithelial cells (16HBE) as control." (PMID 33858449, 2021). "We observed that the mRNA level of ALDOA is positively correlated with PLD1, which is consistent with our findings in lung cancer." (PMID 35127525, 2021). "Further research showed that exosomes containing the metabolic enzymes ALDOA and ALDH3A1 promoted unirradiated lung cancer cells proliferation by accelerating glycolysis." (PMID 33077737, 2020). "The results showed that ALDOA was significantly and positively correlated with the IC50 of cisplatin in lung cancer cells." (PMID 32188842, 2020). "ALDOA (aldolase, fructose-bisphosphate A), one of the NRF2-regulated genes identified in our ChIP-Seq results, promotes the metastasis of lung cancer by activating the HIF-1α/MMP9 axis." (PMID 31884422, 2019). "It is worth noting that, among these identified proteins, five proteins (Hsp90, ENO1, ALDOA, PDIA6, HSPA5) were reported as the differential proteins identified in lung cancer tissues as compared to normal lung in our previous work." (PMID 27684953, 2016). "Interestingly, this opposite trend between ALDOA and FBP1 was also observed in other types of prognosis, such as lung cancer's first progression and post-progression survival." (PMID 35404841, 2022). "Besides being the marker of exosomes, ALDOA, ENO1 and YWHAG can promote metastasis, invasion, activation and proliferation of lung cancer." (PMID 36387251, 2022). "mRNA transcripts of GGT-1, LTC4, FECR1, FECR2, miR-106b, ALDOA, ALDH3A1, and other genes in exosomes derived from lung cancer cells act as important regulators by playing an enabling role in promoting the invasion and migration of lung cancer cells." (PMID 34511114, 2021). "In this study, we provide evidence that ALDOA directly binds to PLD2 to suppress its specific enzymatic activity, resulting in an increase in PLD1 levels and an increase in total PLD enzyme activity to promote lung cancer cell invasion." (PMID 35127525, 2021). "Glycolysis-related enzymes, such as ALDOA with nonenzymatic functions, positively regulate the HIF-1α/ALDOA feedback loops to increase the activation of MMP9 in lung cancer under hypoxia." (PMID 35008539, 2021). "Most importantly, ALDOA and PLD1 have predictive value for the survival of lung cancer patients." (PMID 35127525, 2021). "Furthermore, by combining those genes into a significant prognostic factor for lung cancer patients, we determined that ALDOA, together with TRAF4 or DUSP4, serves as an independent factor for the meta-base and TCGA lung cancer patient cohorts." (PMID 32188842, 2020). "Combining several lines of evidence, we showed that ALDOA promotes lung cancer cell stemness through a nonenzymatic mechanism." (PMID 32188842, 2020). "Finally, we demonstrated a model in which ALDOA coordinates with DUSP4/TRAF4 and is correlated with a poor prognosis in lung cancer patients." (PMID 32188842, 2020). "To investigate whether the ALDOA/PLD1 axis has clinical significance for cancer patients, we performed the immunohistochemical (IHC) staining of ALDOA, PLD1, and PLD2 with specific antibodies in clinical lung cancer samples to validate these findings." (PMID 35127525, 2021).